RNU6-761P (RNA, U6 small nuclear 761, pseudogene)
Gene: Small nuclear RNA gene on chromosome 6 (42,018,408 to 42,018,514, reverse strand). Ensembl gene ENSG00000206875.
Homologues: Orthologues: chimpanzee U6 (99% identical). Paralogues in human: RNU6-25P (95% identical), RNU6-1 (94% identical), RNU6-15P (94% identical), RNU6-2 (94% identical), RNU6-20P (94% identical), RNU6-27P (94% identical), RNU6-33P (94% identical), RNU6-35P (94% identical), RNU6-3P (94% identical), RNU6-4P (94% identical), RNU6-5P (94% identical), RNU6-6P (94% identical), and 1287 more.